GPI (glucose-6-phosphate isomerase)
Diseases named in the same sentence as GPI in open-access papers (continued):
Sharing a sentence is not in itself a finding about the gene and the disease.
Arthritis (continued). "Recently, IL-17-producing Th17 cells have been identified and this T cell population appears to play a critical role in the generation of several types of autoimmune arthritis such as glucose-6-phosphate isomerase (GPI)-induced arthritis and collagen-induced arthritis (CIA)." (PMID 25928901, 2015). "Therefore, we systematically examined the use of 18 F-NaF positron emission tomography/computed tomography (PET/CT) in mice with glucose-6-phosphate isomerase (G6PI)–induced arthritis for quantification of pathological bone metabolism." (PMID 25053370, 2014). "Our results show that artesunate treatment could prevent the onset of arthritis and inhibit anti-GPI antibody production, mediated by abolishing GC B cells." (PMID 25116436, 2014). "Recently, we showed the benefit of state-of-the-art imaging modalities for visualization and quantitative assessment of inflammation in glucose-6-phosphate isomerase (G6PI)–induced arthritis using 2-deoxy-2-18 F-fluoroglucose (18 F-FDG) positron emission tomography/computed tomography (PET/CT)." (PMID 25053370, 2014). "Similarly, in KBxN mice, iNKT cells activated by α-galactosylceramide (α-GalCer) suppressed glucose-6-phosphate isomerase (GPI) peptide-induced arthritis by suppression of GPI-specific CD4+ T cells." (PMID 24286535, 2013). "The arthritis developed faster and was more aggressive as compared with K/BxN mice due to the lack of Treg in the affected joints and an increased production of anti-GPI Ab but the expansion of GPI-specific T-cells was also a likely contributing factor." (PMID 24832045, 2012). "This arthritis appears to be a highly simplified proinflammatory cytokine-induced arthritis; thus, it is similar to the serum transfer-induced arthritis (using anti-GPI antibody-containing sera from arthritic K/BxN mice) and the collagen monoclonal antibody cocktail or LPS-induced arthritis (CAIA)." (PMID 23251214, 2012). "Monoclonal antibodies to TNF-α, IFN-γ, IL-12, CD40L, inducible co-stimulator (ICOS), and cytotoxic T-lymphocyte antigen 4 immunoglobulin (CTLA-4Ig) were used to block TNF-α and IFN-γ production, examine clinical index in mice with GPI-induced arthritis, and determine anti-GPI antibody production." (PMID 18534002, 2008). "Neither Fcγ receptor deficient nor B-cell-deficient mice had overt arthritis, suggesting that anti-GPI antibodies play an indispensable role in this model." (PMID 18534002, 2008). "Immunization with glucose-6-phosphate isomerase (GPI) induces severe arthritis in DBA/1 mice." (PMID 18534002, 2008). "Immunisation with human GPI325–339 could induce polyarthritis similar to arthritis induced by human GPI protein, and administration of anti-IL-17 mAb significantly ameliorated arthritis (p < 0.01)." (PMID 18992137, 2008). "On the other hand, anti-GPI antibody may play a positive role in the progression of arthritis." (PMID 25889507, 2015). "Therefore, the reduction observed in arthritis severity in Padi4 KO mice may be explained by factors other than reductions in anti-GPI antibody levels." (PMID 26293116, 2015). "Autoantibodies directed against joint proteins such as collagen type II or glucose-6-phosphate isomerase (GPI) are found in RA patients, and the arthritis pathology may be modeled in mice by either active immunization with joint-associated components or by passive antibody transfer." (PMID 24910634, 2014). "The goal of our work was to examine, in well-described glucose-6-phosphate isomerase (G6PI)-induced murine arthritis, whether 18F-FDG micro-PET/CT can be used for the quantitative in vivo assessment of inflammation in acute and chronic stages of experimental arthritis." (PMID 21047399, 2010). "However, anti-GPI antibodies from mice with GPI-induced arthritis do not solely cause arthritis (Schubert and coworkers and our preliminary observations)." (PMID 18534002, 2008).
Arthritis (continued). "K/BxN mice express both the T-cell receptor (TCR) transgene KRN and the MHC class II molecule A(g7), and develop autoantibodies recognizing glucose-6-phosphate isomerase (GPI), inducing spontaneous severe arthritis." (PMID 40650132, 2025). "Here, arthritogenic antibodies contained within K/BxN serum bind to ubiquitously expressed glucose-6-phosphate isomerase (GPI) and provoke arthritis independently of T and B cell responses." (PMID 33572654, 2021). "First, only inflammatory arthritis was included in the CAIA model, although there are several models of arthritis such as CIA, adjuvant-induced arthritis, and glucose-6-phosphate isomerase-induced arthritis." (PMID 34006987, 2021). "In the middle-aged group, severe arthritis had already been observed in SFB– mice, and SFB colonization did not further augment arthritis severity and only mildly increased the anti-GPI titers." (PMID 28810929, 2017). "GPI-induced arthritis, a murine model of RA, is induced by immunization of DBA/1 mice with recombinant human GPI (rhGPI)." (PMID 19900268, 2009). "The K/BxN model of spontaneous arthritis is mediated by T cells that express both the T cell receptor (TCR) transgene KRN and the MHC class II molecule A(g7) and by autoantibodies recognizing glucose-6-phosphate isomerase (GPI)." (PMID 34063669, 2021). "In the same work, sclerostin blockade with neutralizing antibody into glucose-6-phosphate isomerase (G6PI) arthritis did not improve arthritis either." (PMID 29472591, 2018). "If RhoB was critical for pathogenic autoantibody production, then serum transferred from the ko KRN.g7 mice should not induce arthritis, even though it contained anti-GPI autoantibodies." (PMID 28882929, 2017). "The sera of the mice contained high titers of antibodies against glucose-6 phosphate isomerase (GPI) peptide, and the disease could be induced in other mice by injecting anti-GPI antibody (K/BxN serum-transfer arthritis)." (PMID 28753982, 2017). "In the murine glucose-6-phosphate isomerase-induced arthritis model, for example, treatment with MTX does not result in decreases in either IL-6 or TNF alpha." (PMID 24444433, 2014). "Arthritis can be induced by injecting serum from K/BxN T cell receptor (TCR) transgenic mice into normal mice, reflecting the high concentrations of arthritogenic autoantibodies recognizing glucose-6-phosphate isomerase (GPI) in the K/BxN arthritis model." (PMID 22314006, 2012). "Surprisingly, when KRN mice were crossed with NOD mice, the progeny, i.e., the KRN Tg TCR in {B6xNOD}F1 mice, developed arthritis with severe joint inflammation, which depended on the presence of Tg TCR and Ab with specificity to glucose-6-phosphate isomerase (GPI)." (PMID 24832045, 2012). "Each of the three different immunisation patterns (rhGPI, hGPI325–339 and hGPI325–339 plus hGPI544–558) showed no positive correlation between anti-mouse GPI antibodies and arthritis score." (PMID 18992137, 2008). "T-helper (Th) lymphocytes are critically required for the pathogenesis of glucose-6-phosphate isomerase (G6PI)-induced arthritis, but neither the G6PI epitopes recognized by arthritogenic T cells nor their pathogenic effector functions have been fully elucidated to date." (PMID 19640302, 2009). "Moreover, the data that transfer of rhGPI-primed or hGPI325–339-primed Th17 cells to naïve DBA/1 mice can not induce arthritis emphasises the necessity of anti-mouse GPI antibodies (unpublished observation)." (PMID 18992137, 2008). "In the GPI-induced arthritis model, anti-GPI antibodies could not induce arthritis on their own." (PMID 18534002, 2008). "In murine glucose-6-phosphate isomerase (G6PI)–induced arthritis, nonremitting arthritis induced by depletion of regulatory T cells led to more severe bone destruction and more persistent thermal hyperalgesia." (PMID 31947680, 2020).
Arthritis (continued). "Another possibility is that the anti-GPI Ig produced in the RhoB ko KRN.g7 animals, although similar in titer to wt, was not able to induce arthritis." (PMID 28882929, 2017).
Dystonia (34 papers, 2010 to 2025). An abnormally increased muscular tone that causes fixed abnormal postures. "GPi has been strongly implicated in the pathophysiology of dystonia, both because of symptoms resulting from injury, and the ability to ameliorate symptoms in a subset of patients using lesions or stimulation in GPi." (PMID 36158959, 2022). "Further studies are, however, needed to evaluate the possible contributions of GPi neuron loss or striatal SP+ neuron loss to the pathophysiology of dystonia in HD." (PMID 24014043, 2013). "It has been proposed that dystonia can be induced by disruption of the cortico-striato-pallido-thalamo-cortical loop and disinhibition of thalamocortical projections caused by blockade of GPi/STN inhibitory fibers." (PMID 40416235, 2025). "One study performed manual image inspection on a cohort of patients with early onset isolated dystonia, identifying an association between an increased number of GPi hypointensities from T1-weighted images and GPi hyperintensities from T2-weighted images, and poorer BFMDRS outcomes." (PMID 37304793, 2023). "For example, many studies have shown t­he inability of the inhibition hypothesis to explain the clinical findings where DBS of GPi can treat dystonia, a condition caused by low-activity GPi." (PMID 33209548, 2020). "Stimulation of GPi in dystonia results in delayed loss of dystonia." (PMID 25368601, 2014). "We substantiated claims of hypo- versus hyperfunctional GPi output in PD and dystonia, while furthermore providing cellular-level validation of the pathological nature of theta and low-beta oscillations in respective disorders." (PMID 39190604, 2024). "We substantiated claims of hyper- versus hypofunctional GPi output in PD versus dystonia, and provided cellular-level validation of the pathological nature of theta and low-beta oscillations in respective disorders." (PMID 39190604, 2024). "These circuit differences would thereby result in increased GPi firing rates (FRs) in PD and decreased rates in dystonia, which has been substantiated by some but not all human single-neuron studies." (PMID 39190604, 2024). "In the second case, with a 3-year follow-up, the genetic form of TOR1A suggested the GPi as a target due to the well-documented significant long-term outcomes in these genetic forms of isolated dystonia." (PMID 39126514, 2024). "The present study investigated oscillatory neural dynamics of GPi in dystonia and PD patients during the IED task." (PMID 36914686, 2023). "This case report presents data from patients with genomic DYT6 dystonia and reveals changes in GPi neurophysiology that coincide with symptomatic improvement, though not as a result of DBS." (PMID 34998426, 2022). "In dystonia, there is increased inhibition of GPe, in the indirect pathway and GPi, in the direct pathway." (PMID 33209548, 2020). "The GPi low-frequency activity correlated with the severity of dystonia and a better outcome was observed if the stimulated contact was close to the maximum low-frequency peak." (PMID 32638036, 2020). "The presence of spontaneous irregular and bursting GPi activity is a feature of both dystonia and Parkinson's disease in adults, so our observation of a reversed pattern with more regular than irregular cells in PANK2-NBIA is intriguing." (PMID 26848170, 2016). "We demonstrate that GPi and GPe firing rates and patterns correlate with dystonia aetiology and phenotype, providing further evidence of differences in the pathophysiology of primary versus secondary dystonia, including PANK2-NBIA." (PMID 26848170, 2016). "We compare the effect of the activity of GPi, the output nuclei of the basal ganglia, on information processing in the downstream neural circuits of thalamus in Parkinson's disease and dystonia." (PMID 24046745, 2013). "By contrast, GPi has limited efficacy in upper extremity dystonia." (PMID 38018482, 2024).
Dystonia (continued). "Our finding of increased GPi activity in the two subjects with dystonia could represent broadening of output predicted by decreased focusing, although it is not clear why the total output would increase." (PMID 36158959, 2022). "In summary dystonia severity appears related to GPi low frequency activity." (PMID 32638036, 2020). "This supports the hypothesis that the activation of the inhibitory output from GPi leads to inhibition of the motor cortex and normalisation of cortical plasticity in dystonia." (PMID 32638036, 2020). "Our results demonstrate that GPi in both Parkinson’s disease and dystonia subjects responded selectively to ‘correct’ feedback and ‘incorrect’ feedback suggesting that outcome valence of motor action is represented in the GPi, especially marked in the theta band in Parkinsonian subjects." (PMID 28246967, 2017). "Based on the evidence involving the GPi in the pathophysiology of dystonia and based on clinical observations that pallidal DBS alleviates off-medication dystonia in PD patients, the GPi has become the target of DBS for dystonia patients with significant clinical improvements." (PMID 20814550, 2010). "Conversely, dystonia has been hypothesized to occur as a result of hypofunctional indirect pathway activity and/or hyperfunctional direct pathway activity, producing decreased GPi-mediated inhibition of thalamocortical motor networks." (PMID 39190604, 2024). "However, if the function of the GPi is potentially altered as has been shown in dystonia, alternative pathways could be utilized, such as antidromic pathways (e.g., from GPi to STN)." (PMID 37638186, 2023). "In this scenario, GPi may be regarded as potentially not necessary in some cases of “tremor associated with Dystonia” phenotype." (PMID 36680569, 2023). "Moreover, a two‐stage CBP of GPi according to its connectivity patterns may be employed for a precise DBS targeting in functional neurosurgery for dystonia." (PMID 32757349, 2020). "For instance, the rodent homologue of the human GPi—EPN—has been utilized in PD and dystonia studies involving DBS interventions." (PMID 39516465, 2024). "The outcome of GPi DBS in other monogenic isolated and combined dystonias including DYT-GNAL (DYT25), DYT-KMT2B (DYT28), DYT-ATP1A3 (DYT12), and DYT-ANO3 (DYT24) have been reported with varying results in smaller numbers of patients." (PMID 33488508, 2020). "The observation that GPi hypoactivity occurs in human generalized and segmental dystonia, as well as in mouse models of DYT1 human dystonia, is consistent with this possibility." (PMID 24014043, 2013). "Even though our findings do not differentiate between GPi and GPe, it is plausible that the observed altered pallidal activity is primarily responsible for the reduced inhibition of dystonia patients." (PMID 40119933, 2025). "This suggests that PPN is a safe DBS target for pediatric secondary dystonia, and that co-stimulation of GPi and PPN may be an effective treatment paradigm for some components of dystonia that are insufficiently treated with GPi stimulation alone." (PMID 37929227, 2023). "This study implicates GPi low frequency activity in dystonia (defined as 6–14 Hz although there are no clear boundaries within this frequency band)." (PMID 30455666, 2018). "Thus, one fundamental pathophysiological change of dystonia may include an imbalance of neurotransmitter levels, which may induce dysfunctional activity mainly via the cortico-striato-GPi direct pathway, resulting in an alteration of GPi inhibitory function on the thalamus." (PMID 24194961, 2013). "Additionally, the study implies that correcting abnormalities in GPi function may explain the effectiveness of DBS targeting the STN and GPi in treating dystonia." (PMID 37389183, 2023). "Thus, the absence of dystonia despite the deficiency in striatal PARV+ interneurons and the occurrence of Tourette symptoms may stem from an alteration in GPi function stemming from its PARV+ neuron excess." (PMID 24014043, 2013).
breast carcinoma (21 papers, 2012 to 2025). "Among the genes of the five proteins selected, GPI, LDHA, TPI1, and ALDOA showed high expression in both breast cancer and colorectal cancer and were associated with poor patient prognosis." (PMID 38419074, 2024). "Although the role of GPI in the development and prognosis of some cancers has been partially elucidated, there were few bioinformatics analyses of GPI expression and function in breast cancer." (PMID 36246907, 2022). "In the present study, according to the analysis of GPI gene expressions in published databases, we evaluated the relationship between GPI expression and the prognosis of breast cancer patients and conducted an analysis of the influence of GPI on the prognosis." (PMID 36246907, 2022). "A couple of works showed that the enzyme responsible for catalyzing the second reaction of glycolysis, glucose-6-phosphate isomerase (GPI), is regulated by miR-200 in breast cancer cells and by miR-302b and miR-17-5p in chicken primordial germ cells." (PMID 31921661, 2019). "Numerous studies have shown that the overexpression of GPI/AMF is connected with poor prognosis, such as tumor invasion and the increased mortality in many cancer types, including gastrointestinal, kidney, lung and breast cancers." (PMID 36968582, 2023). "Glucose-6-phosphate isomerase (GPI) plays an important part in gluconeogenesis and glycolysis through the interconversion of d-glucose-6-phosphate and d-fructose-6-phosphate, and its clinical significance still remains unclear in breast cancer (BRCA)." (PMID 36246907, 2022). "The enzyme glucose-6-phosphate isomerase (GPI) is known to be regulated by miR-200 and miR-302b/miR-17-5p in breast cancer cells and chicken primordial cells, respectively." (PMID 36013278, 2022). "Transcript levels of five of the seven metabolic genes (TALDO1, GPI, SHMT2, LDHA, and ADK: 5-gene metabolic signature) and six oncogenes: TAGLN2, NOLC1, HSP90AB1, HDGF, MCM5, and NCL, were elevated in TNBC patients when compared to patients with ER+ breast cancer." (PMID 34711841, 2021).